GLI1 (GLI family zinc finger 1)
Diseases named in the same sentence as GLI1 in open-access papers (continued):
Sharing a sentence is not in itself a finding about the gene and the disease.
cancer (continued). "Because the SHH-induced target gene products could contribute to the self-renewal, survival, and migration of cancer progenitor cells and Gli1 may play a crucial role in the malignant behavior of PC cells, identifying Gli1 targets is a logical step to understand its mechanism in PC cells." (PMID 22900095, 2012). "Here, we demonstrate that transcription factor glioma-associated oncogene 1 (GLI1) modulates EMT through direct up-regulation of SNAI1 and serves as a downstream effector of the transforming growth factor-β1 (TGFβ1) pathway, a well-known regulator of EMT in cancer cells." (PMID 23185371, 2012). "GLI1 contributes to the invasiveness of pancreatic, prostate, melanoma and glioma cancers." (PMID 21505458, 2011). "GLI1 was included as a central transcriptional effector of the oncogenic Hedgehog (HH) signaling pathway, which is aberrantly activated in GBM and other cancers." (PMID 41596413, 2026). "Our previous research demonstrated a robust correlation between GLI1 and p-S6K1 expression in malignant tumors, particularly among patients with advanced-stage disease." (PMID 39744485, 2025). "Mechanistically, GLI1 directly regulated PRKACB expression, and G4 stabilization downregulated PRKACB, impairing epithelial-mesenchymal transition and cancer stemness." (PMID 40255562, 2025). "GLI1 and PRKACB are highly correlated with cell stemness, so we further explored the correlation with cancer cell stemness." (PMID 40255562, 2025). "Studies have demonstrated a robust correlation between the expression of GLI1 and p-S6K1 in malignant tumors, particularly among patients having advanced-stage tumors." (PMID 39744485, 2025). "Consistently, the expression of mesenchymal biomarkers N-Cadherin, Vimentin and Snail and cancer stemness biomarkers USP37, ALDH1, OCT4 and Smo/Gli-1 in BC cells was suppressed by CYT and markedly recovered by SRSF1 overexpression." (PMID 40176901, 2025). "Differences in GLI1 and SUFU gene expression levels among control tissue, borderline tumors, and carcinomas have been reported by other studies." (PMID 40565349, 2025). "Although small, these differences affected important signaling pathways (NGF-stimulated transcription, IL-10 signaling, PERK activity) and cancer genes (CBFA2T3, ETV4, FGFR1, GLI1, SGK1, and STAT3)." (PMID 38968069, 2024). "To explore the impact of the GLI family on cancer, we investigated how the GLI1, GLI2, GLI3, and GLI1/2/3 gene sets affect tumors." (PMID 38498906, 2024). "The main pathway and genes involved in cancer stem cells include the SHH/GLI-1 signaling pathway, IL6/JAK2/STAT 3 signaling pathway, GLI-1, GLI-3." (PMID 38730691, 2024). "Analysis of cancer genome atlas (TCGA) data has revealed that individuals with CD90+ expression, along with GLI-1 and GLI-3, tend to have a relatively shortened overall survival rate." (PMID 38730691, 2024). "Together, our findings shed new light on the roles of GLI1/2/3 in tumorigenesis and provide a potential basis for the development of novel therapeutic strategies targeting GLI-mediated signaling pathways in cancer." (PMID 38498906, 2024). "Utilizing multiple bioinformatic platforms (TIMER2.0, GEPIA2, and R packages) based on The Cancer Genome Atlas (TCGA) and/or Genotype-Tissue Expression (GTEx) databases, we analyzed the expression of GLI1 in BRCA and its pan-cancer expression profiles." (PMID 39483334, 2024). "We have confirmed the correlation between IL-33 and markers like SerpinA1, SerpinA3, and EphB2 for SCC and Gli1, Gli2, FOXO3A for BCC as it highlights the complex interplay of cytokines, protease inhibitors, and receptor signaling in cancer." (PMID 39839625, 2024). "For example, Gli1 induction of Snail, nuclear localization of β-catenin and subsequent EMT has been documented in several cancers including ovarian, breast, and basal cell carcinoma." (PMID 37954979, 2023).
cancer (continued). "By referring to related literatures and databases, E2F1, GLI1, CDK3, and Mcm4, as candidate target genes, were found to be closely related to the occurrence of cancers, which was very helpful to clarify the mechanism of EZH2 in PC." (PMID 37198697, 2023). "Among dogs with malignant tumours, SHH and GLI-1 expression was significantly higher in metastatic patients (p = 0.01 and 0.007, respectively)." (PMID 37932728, 2023). "Transforming growth factor β (TGFβ) is a strong inducer of both GLI1 and GLI2 in various human cell types, including normal fibroblasts and keratinocytes, as well as cancer cells." (PMID 36674836, 2023). "HDAC11 has an effect similar to that of HDAC1, which is highly expressed in the cancer stem cell population of LUAD, resulting in enhanced self-renewal of lung cancer stem cells and interaction with GLI1 to upregulate SOX2 expression." (PMID 37144123, 2023). "In pathological situations such as cancer, the SHH ligand binds to the PTCH receptor to release SMO and stimulate the translocation of GLI1 into the nucleus in a canonical SMO-dependent way." (PMID 37149646, 2023). "Transforming growth factor beta (TGF-β) was found as a potent inducer of both GLI1 and GLI2 expression in various human cell types, including normal fibroblasts and keratinocytes as well as cancer cell lines such as MDA-MB-231 breast carcinoma cells." (PMID 35163655, 2022). "GLI1 promotes cell proliferation by inducing cyclin D1 expression, while GLI2 is known to increase cancer cell proliferation, tumorigenicity, and metastatic potential." (PMID 35047127, 2022). "SHH binds to the PTCH1 receptor expressed on the cell membrane of osteoblasts and cancer cells, to activate the SHH/PTCH1/GLI1 signaling pathway, which leads to the binding of GLI1 to the promoter of IL-6 and increases the IL-6 expression." (PMID 35285760, 2022). "For example, genistein is known to downregulate the expressions of Gli1 and CD44 while inhibiting the Gli1-related signaling pathway to play a unique regulatory role in cancer stem cell characteristics." (PMID 34209224, 2021). "BCL9 suppression induces phosphorylation of VAV1 in CD8+ T cells and increases GLI1 and PATCH expression to promote CD155 expression in cancer cells." (PMID 34417435, 2021). "When cancer stem-like cells (CD44(+)) treated with genistein inhibited CD44 mRNA and Gli1 protein expressions." (PMID 34336089, 2021). "Recent evidence has outlined the importance of GLI1 and PI3K functioning independently of one another in cancer." (PMID 33658491, 2021). "In human BCC tumors, GLI1 and GLI2 were shown to be significantly elevated biopsy tissues, and GLI1 and GLI2 transcriptionally upregulated basonuclin and cFlip, respectively, to promote cancer cell survival." (PMID 34572373, 2021). "To examine the crosstalk of YAP1 and GLI1, we examined the level of YAP1 protein in cancer cells after the silencing of GLI1." (PMID 34445421, 2021). "The abnormal expression of the transcription factors Gli1 and Gli2 in the Hh signaling pathway regulates the expression of ABCG2 in many cancers." (PMID 34659526, 2021). "GLI1, the first member identified of GLI family, has been widely reported and promotes malignant progression in various cancers via influencing the hedgehog signaling pathway." (PMID 33506047, 2021). "BCL9 suppression blocks VAV1 phosphorylation in CD8+ T cell as well as increases GLI1 and PATCH expression to promote CD155 expression in cancer cells." (PMID 34417435, 2021). "They regulate GLI1 stabilization and GLI1 and GLI2 transcriptional activity in both intact cells and cancer cells." (PMID 32859041, 2020). "When we compared the expression levels of GLI1 and DCLK1 or LGR5 between matched pairs of normal and cancer tissues from CRC patients, we found that their expression levels were negatively correlated with MUCIN-2 expression in cancer tissue." (PMID 32814764, 2020).
cancer (continued). "It has also been observed that in some of the cancer cases even though GLI1 is altered at the initial stages, FOXM1 and GLI1 correlation is seen only when lymph node metastasis occurs." (PMID 33680951, 2020). "In the current study, we have developed a qRT-PCR method to accurately determine the expression levels of SMO, PTCH1, GLI1, GLI2, and GLI3 in a panel of cancer cell lines." (PMID 32784501, 2020). "PI3K-AKT activity induced an increase in the expression of GLI1 and GLI2 in renal cell carcinoma and chronic lymphocytic leukemia (CLL), leading to increased cancer cell growth and progression." (PMID 32245491, 2020). "Studies have shown that GANT61 significantly decreases the transcriptional production and gene expression of GLI1, PTCH1, and other HH pathway target genes, as evidenced by inventoried GLI assays in a range of cancer cell types." (PMID 32846867, 2020). "GLI1 contributes to the cell survival of DLBCL through the expression of AKT in DLBCL and likely in other malignant tumours." (PMID 32206038, 2020). "Recent reports revealed PRMT1, PRMT5, and PRMT7 regulate GLI1 and GLI2 activity in normal and cancer cells." (PMID 32859041, 2020). "Recent studies from our and other groups have shown an interplay between the transcription factor GLI1, the final effector of the Hedgehog (HH) pathway, and the pluripotency transcription factor SOX2 in several types of cancer including melanoma." (PMID 33203881, 2020). "Similar results were observed in other human cancer lines after treatment with GANT61, with inventoried GLI assays demonstrating a reduction in gene and protein expression of the target genes GLI1 and PTCH1, as well as reduced transcriptional production." (PMID 32846867, 2020). "Among the differentially expressed genes, we found that several genes related to cancer progression (HMGA2, PLD2, MMP9, GLI1, GLI2, SLUG and MDR1) were expressed at a low level after knocking out APN." (PMID 32457292, 2020). "Gli1, LSD1, Sox9 were primarily expressed in the nucleus of cancer cells; CD44 primarily located in the membranes of cancer cells." (PMID 32430068, 2020). "Overexpression of GLI1 plays a crucial role in the ATM-mediated DNA damage response (DDR) signaling, anti-apoptosis, drug resistance, EMT, and cancer stemness, resulting in cancer cell survival and progression." (PMID 31783569, 2019). "GLI1 directly induced the transcription of SOX9 and a positive feedback promoting SOX9-dependent cancer stem cell properties was observed." (PMID 31057614, 2019). "Protein expression of GLI1 was reduced by MEP50 or PRMT5 knockdowns, suggesting that MEP50/PRMT5-mediated activation of HH signalling operates in HH-expressing cancer cells." (PMID 30675521, 2019). "In conclusion, they showed that estrogen promotes cancer stem cell development and EMT through GLI1." (PMID 31394751, 2019). "Similar to the results we obtained in peritoneal MCAs from patient samples, the protein levels of Integrin αvβ3, p-ERK1/2, and GLI1 were higher in BGC823 MCAs and SGC7901 MCAs than in scattered-free cancer cells." (PMID 31366904, 2019). "GLI1 binds to IL-6 promoter and fibroblasts-secreted IL-6 regulates activation of STAT3 in cancer cells." (PMID 31847096, 2019). "Oncogenic KRAS induces the expression of Sonic Hedgehog (SHH) in cancer cells, whilst SHH induces expression of the transcription factor GLI family zinc finger 1 (GLI1) in fibroblasts." (PMID 31847096, 2019). "Studies have demonstrated the important role of GLI1 overexpression in the deregulation of the DDR and repair signaling in cancer cells for their survival during oncogenic stress and to develop chemoresistance." (PMID 31783569, 2019).
cancer (continued). "While TGF-β is important for SMO-mediated cancer development, its role in the induction of GLI2 and GLI1 expression by inhibition of PKA activity has also been reported." (PMID 31202261, 2019). "GLI1 increases metastatic potential by tuning up the levels of the CXCR4/CXCR7 receptors in BC cells and in other cancers." (PMID 31027259, 2019). "The quick overview of the Catalogue of Somatic Mutations in Cancer (COSMIC) database shows that there are about 100, 30 and 60 sequence variants that could a priori be considered as pathogenic (nonsense substitutions and frameshift indels) found in GLI1, GLI2 and GLI3, respectively." (PMID 30158435, 2018). "Upregulation of GLI1, or downregulation of I-SMAD, both of which have been observed in various cancer cells, also decrease the threshold for generating the second SNAIL1 wave." (PMID 29872541, 2018). "Another developmental pathway aberrantly active in some cancers, the Wnt/β-catenin pathway, shares reciprocal interactions with HH-GLI signaling on level of GLI1 inducing expression of SNAIL or sFRP1." (PMID 30158435, 2018). "Signal transduction genes (i.e., ADCY4/7/8/9,) are also in the list of our 102 genes, which also includes cancer stem cell signaling genes (i.e., WNT7A, GLI1/2/3, NOTCH2/3/4, ALDH1A3)." (PMID 29304754, 2018). "The HH signaling pathway, acting through transcription factors GLI1, GLI2, and GLI3, has been identified as critical for the initiation and progression of a number of cancers." (PMID 30201866, 2018). "While knockdown of GLI1 and GLI2 sensitized cancer cells to 5-FU, the IC50 was still higher than the parental cells." (PMID 28413604, 2017). "Examples of TFs that control morphogenesis and play a role in cancer that were identified to oscillate in our data include PAX6 and GLI1." (PMID 29228002, 2017). "To determine the molecular mechanisms underlying Gli1-mediated 5-FU resistance in LoVo-R cells, we characterized LoVo-R cells with GLI1-shRNAs or GLI2-shRNAs for cell morphology, EMT and expression of cancer stem cell markers." (PMID 28413604, 2017). "Target genes of hedgehog signaling include GLI1, PTCH1 as well as other molecules involved in regulation of cancer cell function, such as ABCG2." (PMID 28404967, 2017). "We have data to show that knocking down GLI1 or inhibiting ABCG2 functions, sensitizes cancer cells to chemotherapy in cultured cells and in mice." (PMID 28404967, 2017). "Transcription factors GLI1 and OCT4 are involved in a control of self-renewal of both somatic stem cells and cancer stem cells." (PMID 28030801, 2017). "It decreased GLI1 and PTCH1 mRNA expression in vitro and inhibited proliferation of several cancer cell lines." (PMID 26891329, 2016). "The GABA-induced reduction in the expression of CD133, ALD-1, SHH, Gli-1 and SOX9 thus suggests significant inhibitory effects of GABA on cancer stem cells as contributing factors to the observed PDAC prevention in the current study." (PMID 27281617, 2016). "GANT-61 has shown potent inhibition of GLI1 and GLI2 in many cancer cell lines, including rhabdomyosarcoma, osteosarcoma, neuroblastoma, and ovarian cancer." (PMID 26891329, 2016). "Both GLI1 and GLI2 are oncogenes, can induce transformation and tumorigenesis, and are constitutively activated in many types of human cancers." (PMID 27863397, 2016). "The ability of tGLI1 to activate cancer-mediating genes like CD24, VEGF-A, MMP-2, and MMP-9 make it more potent transcriptional regulator than GLI1 or GLI1ΔN." (PMID 25985215, 2015). "The dysregulated expression of GLI1 and GLI2 plays a crucial role in the development and progression of many types of human cancers, including PDAC." (PMID 26318045, 2015). "Both GLI1 and GLI2 act as main mediators of HH signalling in cancer by controlling the expression of target genes." (PMID 25660620, 2015). "On the other hand, downregulation of GLI1 transcriptionally repressed ABCG2 and sensitized cancer cells to chemotherapeutic agents." (PMID 26633513, 2015).
cancer (continued). "Treatment with recombinant Shh resulted in significant upregulation of Hh target genes such as Gli1 and Foxl1 in BBF2H7-expressing cancer cell lines and enhanced cell growth." (PMID 25955804, 2015). "We constructed a retrovirus vectors carrying the Gli1 gene, and transduced it into four gastric (SH-10-TC, MKN1, NCI-N87, AZ-521), one colorectal (WiDr), and three other cancer cell lines (MDA-MB435, T98G, A172)." (PMID 25166306, 2014). "Both GLI1 and GLI2 are oncogenes, induce transformation and tumorigenesis, and are constitutively activated in many types of human cancers." (PMID 24962990, 2014). "Thus, in ESCC patients subjected to CRT, the role of BMI1-mediated inhibition of p16INK4A protein is not clear, and the clinical effect of Hh signalling pathway activation might be more evident than that of the presence of BMI1, whilst BMI1and Gli-1 both play important roles in cancer progression." (PMID 23046527, 2012). "It's interesting to note that though both MS-0022 and GDC-0449, and to a certain degree cyclopamine, led to a reduction of GLI1 mRNA in SUIT-2 cells in vitro, suggesting the possibility to affect autocrine Hh signaling in this cancer cell line." (PMID 21698280, 2011). "The preferential expression of cancer stem cells related marker (CXCR4), regulatory genes (BMI1, GLI1, and GLI2) and microRNAs (miR-214, miR-21, miR-221, miR-222 and miR-155) in holoclones were also highlighted." (PMID 21826251, 2011). "Further, it has been proposed that GLI-directed compounds that block growth in one cell type may be ineffective in others and indeed, it may be necessary to directly screen specific cancer cell lines for compounds that specifically inhibit GLI1 expression in a particular cellular context." (PMID 21505458, 2011). "Network analysis pinpointed specific regulatory hubs, such as SOX2 and SERPINE1 for HPV16, and ERBB4 and GLI1 for HPV18, which may facilitate malignant tumor growth by disrupting metabolic, keratinization, and extracellular matrix pathways." (PMID 41993883, 2026). "Inhibiting the function of GLI1/GLI2 using a pharmacological inhibitor or a truncated GLI3 repressor mutant led to decreased protein levels of hTERT and reduced telomerase activity in various cancer cell lines." (PMID 41301813, 2025). "Even in tumors with elevated expressions of the HH target genes GLI1 and PTCH1, the expression of SHH, as a canonical driver of the HH pathway, is not necessarily high, suggesting other mechanisms of HH signaling activation in cancer." (PMID 40565349, 2025). "Hence, the combined inhibition of GLI1 and GLI2 using the GANT61 inhibitor and AKT inhibitor Perifosine has been shown to inhibit cancer cell growth and promote apoptosis." (PMID 38498906, 2024). "Notably, one analog, BAS 07019774, effectively decreased Gli1 mRNA expression in an Hh-responsive cell line model and reduced cell viability in GLI-dependent cancer cell lines." (PMID 38999049, 2024). "By utilizing different cancer single-cell datasets, we gained an understanding of the expression distribution of GLI1, GLI2, and GLI3 at the single-cell level and found that GLI1, GLI2, and GLI3 were mainly highly expressed in fibroblasts." (PMID 38498906, 2024). "This could explain the observed higher effectiveness of BAS 07019774 in reducing the viability of cancer cell lines expressing both GLI1 and GLI2 (U87MG and SK-MES-1) compared to T98G cells, which primarily express GLI1." (PMID 38999049, 2024). "Moreover, the inhibition of MMR pathways observed in our study aligns with previous reports indicating that GLI1 can interfere with MMR, potentially leading to genomic instability and accelerated cancer progression." (PMID 39483334, 2024).